EGFR (epidermal growth factor receptor)
Diseases named in the same sentence as EGFR in open-access papers (continued):
Sharing a sentence is not in itself a finding about the gene and the disease.
tumor (continued). "Our study is limited only to the quantification of cfDNA and should also be analyzed for tumor-specific genomic alterations in cfDNA such as EGFR and KRAS for more precise efficacy prediction and personalized treatment selection." (PMID 37710221, 2023). "EGFRvIII provided a homing signal for CAR-T cells, and the activated CAR-T cells secreted CD3/EGFR BiTE and mobilized bystander T cells against tumor cells with high EGFR expression." (PMID 37596653, 2023). "In this context, we selected the tumor types that also showed a moderate or high correlation between EGFR, MET and PD-L1." (PMID 37370859, 2023). "Human epidermal growth factor receptor 2 (HER2) pertains to the epidermal growth factor receptor (EGFR), which is related to proliferation, apoptosis, and tumor cell migration." (PMID 37065861, 2023). "Nimotuzumab is a non-intrinsically stimulating anti-EGFR monoclonal antibody that blocks the binding of EGFR to its ligand and exhibits anti-angiogenic, anti-tumor cell proliferative, and pro-apoptotic effects in EGFR-overexpressing tumors." (PMID 37996813, 2023). "We measured changes in tumor volume for >50 d in mice treated with encorafenib (BRAF inhibitor) ± panitumumab (EGFR inhibitor) ± celecoxib (COX2 inhibitor)." (PMID 36759733, 2023). "Dual-RevCAR T cells armed with the combination of RevTM EGFR-7B6 + GD2-5B9 or RevTM EGFR-7B6 + GD2-IgG4-5B9 were able to induce significant tumor lysis." (PMID 37122703, 2023). "Correspondingly, we consider that suppression of tumor cell metabolism by EGFR-TKI treatment potentially results in a low accumulation of FDG-PET." (PMID 37719531, 2023). "EGFR amplification has been observed in 57% of GBM and is associated with enhanced tumor cell angiogenesis." (PMID 37686092, 2023). "Results showed that arsenic exerted an inhibitory effect on the primary tumor cells harboring EGFR WT, L858R, ΔE746-A750, and T790M genotypes." (PMID 37371816, 2023). "In this view, the phage display technique allows a rapid selection of peptide ligands for membrane receptors, such as EGFR overexpressed on tumor cells, as an alternative and powerful tool for the development of anticancer strategies." (PMID 37048151, 2023). "EGFR vIII is a typical tumor-specific antigen that is highly expressed on the cell surface of GBM and other tumors, while it is low or absent in normal tissues." (PMID 37190280, 2023). "In the L-sided tumor group, RR was 43% in patients treated with anti-EGFR and 0% in patients treated with R/T (p <0.0001)." (PMID 36895480, 2023). "The experiments also showed that the switch between AR signaling and EGFR signaling is mediated by HS3ST1 in tumor formation and growth." (PMID 37463954, 2023). "In another study, tumor imaging was possible as early as 3 h following the administration of radiolabeled anti-EGFR VHHs, compared to 16 h for radiolabeled anti-EGFR mAbs." (PMID 37746282, 2023). "We also observed tumor samples with co-occurring driver variants in EGFR, KRAS, and BRAF genes (seven patients with KRAS/EGFR variants; four patients with BRAF/KRAS; one patient with BRAF/EGFR/KRAS)." (PMID 37483495, 2023). "Truncal and private genetic alterations, including the complex local genomic instability of EGFR, identified in 2 CE and 9 NE samples were used to infer the molecular trajectory of tumor evolution." (PMID 37770427, 2023). "In contrast to VM, presence of CD31 or CD34 in cells that co-expressed tumour markers (e.g. EGFR amplification) or stem cell markers (e.g. CD133, Nestin) indicated vessels containing endothelial cells resulting from transdifferentiation of GSCs." (PMID 36823554, 2023).
tumor (continued). "The authors analyzed the cerebrospinal fluid cell‐free tumor DNA from patients with epidermal growth factor receptor (EGFR)‐mutant non‐small‐cell lung cancer and leptomeningeal metastasis." (PMID 36977550, 2023). "A primary mechanism of gefitinib is that it interferes with the metabolic functions of tumor cells and inhibits EGFR signaling in a meaningful manner." (PMID 36777726, 2023). "We next studied more in detail the CBX3 copy number (CN) status in tumor samples displaying either diploid or amplified EGFR gene." (PMID 37633946, 2023). "They reported an increase in tumor cell proliferation, anti-epidermal growth factor receptor (EGFR) expression, and epithelial to mesenchymal transition when HNSCCs were cultured with cancer fibroblasts." (PMID 37568710, 2023). "Our results indicate that AuNP-NmAb showed improved anti-tumor activity and cellular uptake towards EGFR-overexpressing cancer cells over free NmAb." (PMID 37623652, 2023). "A recent study found that nerve‐derived NGF induces EMT and confers tumor cell resistance to the EGFR inhibitor erlotinib in HNSCC." (PMID 36039037, 2023). "Anti-EGFR VHHs fused with iRGD significantly improved penetration and were able to reach the core area of the tumor mass in established multicellular spheroids." (PMID 37746282, 2023). "CLDN2 expression increased cellular proliferation, anchorage-independent growth and tumor growth in vivo, potentially via the epidermal growth factor receptor (EGFR) transactivation, a key regulator of colorectal carcinogenesis." (PMID 36672179, 2023). "HDGF was increased by gefitinib administration in PC-9 xenograft tumors with HDGF overexpression (P < 0.05), and other changes in HDGF and p-EGFR in tumor tissues were consistent with the cell experiments." (PMID 37301856, 2023). "EGFR is related to tumor cell proliferation, angiogenesis, tumor invasion, metastasis, and inhibition of apoptosis." (PMID 37149605, 2023). "Beclin-1 is regulated by EGFR, whose overexpression decreases Beclin-1 levels and promotes tumour progression." (PMID 37174088, 2023). "Nevertheless, the discovery that the MAPK and EGFR pathways appear dysregulated in this tumor subtype has led to the identification of various therapeutic targets that have shown promise in clinical strategies." (PMID 37221626, 2023). "Immunohistochemistry of the tumor sections demonstrated that EGFR expressions were suppressed by 35d in vivo." (PMID 37178919, 2023). "Previous published results showed that EGFR contributes to the cellular response to stress by upregulating the transcription of the EGFR gene and modulating miRNA biogenesis in tumor cells." (PMID 37114127, 2023). "S100A4 can enhance EGFR/ErbB2 receptor signaling pathway to induce cell proliferation and promote tumor progression." (PMID 37873538, 2023). "On the other hand, active targeting is achieved by delivering GNPs with tumour-specific targeted receptors/antigens for example GNP-conjugated EGFR monoclonal antibodies for binding with over-expressed receptors on tumour cells." (PMID 38112935, 2023). "This case highlights the heterogeneity of this tumor, which is still a major challenge for EGFR-targeted GBM therapy, together with the limited brain permeability of most TKIs and the low specificity of small molecules inhibiting GBM-related EGFR mutations." (PMID 36985576, 2023). "The link between DNA repair mechanisms and epidermal growth factor receptor (EGFR) signaling has been reported in many human tumor cells." (PMID 37762316, 2023). "EGFR inhibitors can reduce the growth of tumor cells through disruption of the signaling pathway (Ras)." (PMID 37901797, 2023). "Subsequently, the authors evaluated the role of EGFR-rich EVs both in vivo (tumour tissues) and in vitro (high and low metastatic NPC cell lines)." (PMID 37296932, 2023).
tumor (continued). "Overexpression of the epidermal growth factor receptor (EGFR) induces tumour growth and is involved in regulating DNA damage response in preclinical studies." (PMID 37430137, 2023). "One of the most notable characteristics of HNSCC is that 90% of the tumors overexpress epidermal growth factor receptor (EGFR) to promote tumor growth." (PMID 37898690, 2023). "From the various research and trials carried out, it stands out that a positive association exists between EGFR and/or EGF family ligand status and various clinicopathological features of advanced tumor or grave prognosis." (PMID 38090376, 2023). "Dividing the EGFR-mutant NSCLC patients into two subpopulations based on YAP1 expression, we found that patients with YAP1_High tumor had immunosuppressive immune cells and inferior prognosis in EGFR-mutant NSCLC patients compared to those with YAP1_Low tumor." (PMID 37388902, 2023). "An additional anti‐EGFR mAb (cetuximab) was also added to enable these NPs to target GBM tumor cells with increased EGFR expression." (PMID 37206213, 2023). "After the introduction of EGFR-specific nanobodies, the exosomes showed significantly increased binding ability to EGFR-overexpressing tumor cells." (PMID 36593970, 2023). "Our results confirmed the predictive role of the primary tumor site for third-line anti-EGFR-based treatment in RAS/BRAF wt patients." (PMID 36895480, 2023). "Numerous studies and several pioneer factors, such as EGFR, IL-6, TGFβ revealed that liver regeneration and tumor development are inseparable process." (PMID 37315292, 2023). "CAR-NK is particularly suitable for inducing the recognition and lysis of tumor cells overexpressing EGFR on various tumor cell surfaces, such as breast, lung, and carcinoma." (PMID 37349810, 2023). "Upregulated expression of FUT8 in cancer-associated fibroblasts promotes the construction of an invasive tumor microenvironment in NSCLC through the core fucosylation of EGFR." (PMID 37256139, 2023). "Despite an initial response to EGFR TKIs, almost all patients develop tumor progression and acquired resistance to EGFR TKIs within one to two years." (PMID 37766136, 2023). "Chemokine-like factor like MARVEL transmembrane domain containing 7 (CMTM7) is reported as a tumor suppressor and is involved in epidermal growth factor receptor degradation and PI3K/AKT signaling in previous studies." (PMID 36829181, 2023). "Overall, intracellular signaling pathways induced by the EGFR/ErbB family promote processes that are favorable to tumor progression, with the more described ones being survival and proliferation." (PMID 38255679, 2023). "Costimulatory BiTEs targeting a variety of solid tumors are currently evaluated in phase I/II trials: MUC16, PSMA, EGFR, PD-L1, HER2, Nectin-4, and FAP (targeting tumor-associated fibroblasts)." (PMID 37332039, 2023). "The EGFR signaling complex initiates a number of signaling cascades that are crucial in tumor proliferation, motility, differentiation, and survival." (PMID 38201528, 2023). "EGFR expression at the plasma membrane of tumor cells was also observed in our PTC samples which correlate with the p38 heterogenous pattern in our samples." (PMID 37114127, 2023). "The combination of theasinensin A and nimotuzumab has a remarkable inhibitory effect on NSCLC tumor growth by means of inhibiting the EGFR signaling pathways and the tumor microenvironment." (PMID 37762316, 2023). "To explore the application of multi-target drugs in anti-tumor, we synthesized ten new dual-target inhibitors targeting EGFR and ALK simultaneously with ceritinib as the lead molecular." (PMID 36903251, 2023). "The binding of tumor-targeted superantigen-based peptides to EGFR on MDA-MB-468 cells was assessed by ArrayScanTM XTI." (PMID 37445686, 2023).
tumor (continued). "Functionally, SPINK1 overexpression promotes tumor initiation, self-renewal, and chemoresistance by driving a deregulated EGFR-ERK-CDK4/6-E2F2 signaling axis to induce dedifferentiation of HCC cells into their ancestral lineages." (PMID 38030644, 2023). "EGFR was found to be overexpressed in a total of 79 samples (95%), also exhibiting a significant (p = 0.045) difference in distribution between tumor sizes." (PMID 37623256, 2023). "The most promising ADC developed using this strategy (mAbE-21a, derivative 11, DAR7.5) demonstrated remarkable anti-tumor activity with complete remissions at 0.25 mg/kg in an EGFR+ model." (PMID 36650546, 2023). "Tumour biopsy is the preferred approach for EGFR molecular testing, but in up to 30% of the cases, tissues are not available or their quality is inadequate for molecular testing." (PMID 37047382, 2023). "In this scenario, the cetuximab–VC–DOX targeting tumor cells overexpressing epidermal growth factor receptor (EGFR) was adsorbed on BSA nanoparticles (NPs) synthesized via desolvation." (PMID 37514035, 2023). "This discrepancy can be explained by the fact that the “pathologist-determined tumor” contains regions of non-EGFR–expressing tissue, and PAI is designed to enhance contrast as a function of targeted molecule (in this case, EGFR expression)." (PMID 34651290, 2023). "Among patients with R-sided tumor, 9 (47%) were treated with anti-EGFR-based therapy and 10 (53%) with R/T." (PMID 36895480, 2023). "On the other hand, both EGFR antibodies significantly reduced the overall MDA-MB-468 tumor cell number compared to control mice treated with the respective isotype control antibody." (PMID 37346044, 2023). "The tumor immune microenvironment of EGFR mutant LUAD patients has reduced infiltration of CD8+ T lymphocytes and induced increased production of Treg, which is consistent with our results through database analysis." (PMID 36756152, 2023). "In early clinical trials, both combination TKI therapy, and combination TKI and antibody, antibody-drug-conjuate, and bi-specific EGFR-MET antibody have shown anti-tumor activity." (PMID 37296959, 2023). "The surface of the exosomes expressing HER2-LAMP2B fusion protein promoted tumor-specific uptake via epidermal growth factor receptor (EGFR)-mediated endocytosis." (PMID 37345176, 2023). "The study was further performed on six patients with a history of everolimus and EGFR-TKI treatment to estimate the anti-tumour activity." (PMID 37686122, 2023). "At the membrane, β-catenin and the AJ complex promotes EGFR stabilization and signaling, which allows tumor survival." (PMID 38173713, 2023). "EGFR aptamer–coupled EGFR-SNPs were designed to efficiently deliver SaL, enhancing OS cytotoxicity, inhibiting tumor sphere formation, and reducing the proportion of CD133 + OS stem cells (OSCs)." (PMID 36944946, 2023). "EGFR-specific mAbs function similarly by disrupting pro-tumor growth and survival signaling through binding to growth factor receptors, thus altering their activation state or preventing ligand binding." (PMID 38201251, 2023). "Comparable to the two-in-one antibody HCP-LCE, it exhibits specific cellular binding to EGFR and PD-L1 double positive tumor cells, blocks the PD-1/PD-L1 axis and mediates a potent ADCC effect as an NKCE." (PMID 37081888, 2023). "The selected EGFR tyrosine kinase inhibitors (TKIs) were approved for the treatment of several tumor types." (PMID 36769112, 2023). "The probability of total- and phospho-EGFR expressions in pre-alectinib-treated tumor cells was evaluated using immunohistochemical staining." (PMID 36702855, 2023). "High levels of EGFR were detected in approximately 50% of the tumor cell cultures (WG0, WG1, WG2, WG4, WG9, WG10, WG13, WG18)." (PMID 36900355, 2023).
tumor (continued). "A study developed a model, called EVsum5, based on the combination of LMP1, LMP2A, and the tumor markers programmed death 1 (PD-L1), epidermal growth factor receptor (EGFR), and epithelial cell adhesion molecule (EpCAM) to identify five EV subpopulations." (PMID 36968209, 2023). "Approximately 30–50% of mCRC patients develop RAS mutant cancer cell clones during anti‐EGFR therapy, which leads to disease progression after initial anti‐tumor response." (PMID 36880426, 2023). "As one member of GALNT family, GALNT2 is dysregulated in many types of cancers, and plays tumor suppressive or promoting roles via regulating protein O-glycosylation, such as epidermal growth factor receptor and AXL receptor tyrosine kinase." (PMID 37993881, 2023). "EGFR amplification is known to accelerate tumor angiogenesis and the induction of proangiogenic factors; increased DSC-CBV, and DCE-Ktrans have been reported in EGFR-amplified GB." (PMID 36830900, 2023). "EGFR inhibitors can also impact on T cell tumor antigen recognition, activation, and trafficking of immune cells into the tumor." (PMID 36551637, 2022). "In addition, the confirmation of EGFR gene mutation provides possible treatment sites and the possibility of individualized treatment for patients, which is likely to elucidate the therapeutic prospects of controlling tumor development by targeting specific molecules." (PMID 35734411, 2022). "In the multivariate analysis, after the adjustment for ECOG PS, smoking status, tumor grade, clinical stage, EGFR status and type of response to first-line therapy, the LKB1-positive expression remained a significant factor for PFS (HR 0.20 (0.11–0.38))." (PMID 36661676, 2022). "Western blotting further proved that the expression of Notch3, as well as β-catenin downstream genes CBP (Lys1535)/p300 (Lys1499) and p-EGFR (Tyr1068) in the tumor tissues, was reduced." (PMID 35463301, 2022). "Upregulation of PD-L1 by various oncogenic mutations such as EGFR, BRAF, and activation of PI3K and JAK-STAT3 in tumor cells are critical pathways modulating tumor immune responses in the TME." (PMID 36361831, 2022). "As an example, multimerization of the anti-EGFR 7D12 nanobody with other VHH domains has successfully led to the inhibition of tumor growth in vivo." (PMID 35232398, 2022). "Here, we demonstrate that the tumor microenvironment protects CR-CSCs from EGFR/HER2, BRAF and PI3K targeting, promoting CD44v6 and Myc expression." (PMID 35158939, 2022). "We reviewed records for patients who were initially noted to be RAS/RAF wild-type on tissue, who received prior anti-EGFR therapy and then subsequently had at least one circulating tumor DNA-based testing." (PMID 35837097, 2022). "Numerous variables, such as disrupted signaling caused by somatic mutations in the EGFR-mediated RAS/RAF/MAPK, PI3K/AKT, JAK/STAT signaling cascade, supports tumour survival in one way or another." (PMID 36620544, 2022). "The added advantage of the EGFR PET is to evaluate tumor EGFR TKI sensitivity when regular biopsies are not informative enough or for obtaining spatial insights in the tumor TKI sensitivity to guide decision-making." (PMID 36313723, 2022). "Although celecoxib combined with palliative therapy showed no improvement in patient survival and the local control of the tumor, EGFR wild-type patients had a prolonged PFS with celecoxib-combined therapy (HR = 0.57, 95%CI = 0.35–0.94)." (PMID 36135051, 2022). "The expressed antibody binds to the GPI anchoring signal peptide on the surface of the exosomes so that the exosomes can target and bind to tumor cells expressing EGFR." (PMID 36304147, 2022). "The use of matched therapy was relatively low in patients with tumor alterations such as ERBB2 mutation (14/43, 32.6%), MET amplification (32/99, 32.3%), KRAS G12C (8/135, 5.9%), and EGFR exon 20 insertion (1/25, 4.0%)." (PMID 35877242, 2022).